CHGA (chromogranin A)
Diseases named in the same sentence as CHGA in open-access papers (continued):
Sharing a sentence is not in itself a finding about the gene and the disease.
tumor (continued). "However, one tumor (T20) exhibited widespread CHGA positivity, and morphology distinctive of neuroendocrine prostate cancer (NEPC)." (PMID 25155515, 2014). "A few scattered cells among the tumour mass revealed a weak chromogranin-A reaction." (PMID 24602387, 2014). "However, although the data suggested that most tumors were responding to androgen deprivation therapy at the time of tumor collection, four tumors displayed elevated CHGA expression at the mRNA level." (PMID 25155515, 2014). "A few scattered cells among the tumour mass revealed weak chromogranin A immunoreactivity." (PMID 24602387, 2014). "Chromogranin A (CgA) is the most commonly used general tumor marker at the moment." (PMID 24282616, 2013). "Immunohistochemically, the tumor cells were positive for synaptophysin and chromogranin A." (PMID 24099520, 2013). "Immunohistology revealed expression of the neuroendocrine marker chromogranin A in tumor cells." (PMID 22253802, 2012). "Collection of tumor marker data, for example, Chromogranin A, as well as functional parameters, for example, PET, may help to overcome some of these shortcomings." (PMID 22235376, 2011). "The tumor cells were positive for neuroendocrine markers chromogranin A and synaptophysin." (PMID 20591162, 2010). "Our observations have shown that all the applied antibodies are useful in differential diagnosis of neoplastic processes located at the cardiac base but only chromogranin A may help in evaluation of tumour malignancy." (PMID 20492718, 2010). "Serum for chromogranin A estimation and pharmacokinetics was available from 59 patients (94%), and tissue was available for IHC analysis of somatostatin receptors from 20 samples from 19 patients (44%); one patient had two tumours." (PMID 16953241, 2006). "However, our approach was limited by the unavailability of tumour markers such as chromogranin A and serum gastrin, which could have provided additional diagnostic and prognostic information." (PMID 41169289, 2025). "Chromogranin A (CHGA) may play a role in early tumor progression." (PMID 40906438, 2025). "Additionally, combining NLR with other biomarkers such as chromogranin A, circulating tumor cells (CTCs), or transcriptome profiles might improve prognostic accuracy in specific patient populations, notably in gastrointestinal malignancies and NSCLC." (PMID 40556676, 2025). "Some tumor sections were immunostained with ready-to-use primary antibodies against broad-spectrum cytokeratin (CK), vimentin, calretinin, Wilms tumor gene-1 (WT-1), D2–40, Paird box 8, synaptophysin, chromogranin-A, inhibin-α, S-100, Melan-A, HMB45, CD34, and Ki-67 (Maixin, Fuzhou, China)." (PMID 38115250, 2023). "The tumor can stain positive for synaptophysin in 75% of NECs, followed by chromogranin A. In cases of functional NEC, urine 5-hydroxyndoleacetic acid and nuclear imaging studies, such as somatostatin scintigraphy or MIBG, may be useful for diagnosing and evaluating the therapeutic response." (PMID 35653037, 2022). "Human chromogranin A (CgA), a 439 residue-long member of the “granin” secretory protein family, is the precursor of several peptides and polypeptides involved in the regulation of the innate immunity, cardiovascular system, metabolism, angiogenesis, tissue repair, and tumor growth." (PMID 36559048, 2022). "However, if a NET is negative for synaptophysin, then a different marker for neuroendocrine differentiation (e.g. chromogranin-A) could be used to identify tumor cells." (PMID 32632119, 2020). "Chromogranin A reflects tumor burden and may be used to assess the speed of tumor growth." (PMID 32708330, 2020). "Human chromogranin A could be detected in the plasma of all mice with xenografted GOT1 tumours." (PMID 30730850, 2019). "Both Merkel cells and the tumor cells found in MCC express neuroendocrine markers, including chromogranin-A." (PMID 41210275, 2025).
tumor (continued). "Chromogranin A (CgA) is the most widely used serum marker, elevated in 60–100% of NET patients and generally correlating with tumor burden." (PMID 40869648, 2025). "Daily oral administration of HOC in a nude mouse NEPC xenograft model markedly suppressed the tumor expression of EPHA3 and BRN2, along with their downstream effectors EZH2, ASCL1, and DLL3 and neuroendocrine markers SYP and CHGA." (PMID 41514539, 2025). "Nonetheless, an analysis of metastatic versus non-metastatic COAD tissue revealed that EEC-related genes (GCG, PYY, CHGA, NEUROD1) were consistently downregulated in both tumor and normal tissue and between metastatic and normal tissue." (PMID 41303610, 2025). "Another significant factor is the neuroendocrine-specific marker chromogranin A, which has been shown to promote the proliferation of NEC cells and modulate the tumor microenvironment by inhibiting fibroblast adhesion within the tumor." (PMID 40909957, 2025). "Representative sellar tumor samples displayed immunoreactivity for pituitary NET markers, such as chromogranin A, synaptophysin, S100, and CD56/NCAM36,41,42." (PMID 41203869, 2025). "Tumor cells expressed 2 or more neuroendocrine markers: synaptophysin (SYN) 100 % (4/4), CD56 100 % (4/4), and chromogranin A (CgA) 50 % (2/4)." (PMID 41305788, 2025). "To verify whether monocyte- and macrophage-CM modulate the tumor plasticity of SCC cells, we analyzed the expression of genes associated with epithelial-mesenchymal transition (EPCAM, SOX2), stemness (NANOG, MYC, EZH2), and neuroendocrine differentiation (CHGA, AURKA, MYCN)." (PMID 41259557, 2025). "The tumor from our patient demonstrated coexpression of epithelial markers AE1/AE3 as well as neuroendocrine markers including synaptophysin, chromogranin A, INSM1, and CD56." (PMID 40843719, 2025). "We further validated the expression of Chromogranin A, Synaptophysin, PAX6 and NCAM1 using immunohistochemistry staining on MAP model tumor sections." (PMID 38609433, 2024). "In all specimens, CHGA, SSTR2, and SYP exhibited strong staining in the (ductal) epithelial tumor cells." (PMID 39682758, 2024). "By delving deeper into the characterization of GC cells, we identified 6 specific tumour cell subtypes: C0 PSCA+ tumour cells, C1 CLDN7+ tumour cells, C2 UBE2C+ tumour cells, C3 MUC6+ tumour cells, C4 CHGA+ tumour cells and C5 MUC2+ tumour cells." (PMID 38894657, 2024). "Factors including tumour growth rate (TGR), elevated chromogranin A (CgA) levels, and presence of lung metastases were also predictive of PFS or OS." (PMID 39061146, 2024). "Immunohistochemical analysis of tumor cells revealed the following results: AE1/AE3(+), TTF-1(–), p40(–), chromogranin A(–), synaptophysin(–), CD56(–), INSM1(–)." (PMID 39463789, 2024). "Multiple image-based features including total and organ-specific tumor volume and SSTR density along with clinicopathological biomarkers including Ki-67, chromogranin A (CgA) and alkaline phosphatase (ALP) were analyzed with respect to the PRRT response." (PMID 38948061, 2024). "SCLC is the most common form of neuroendocrine lung cancer and produces the classic neuroendocrine markers, Chromogranin A, synaptophysin, NCAM (CD56) and Calcitonin gene-related peptide (CGRP), which are commonly used as SCLC tumor markers." (PMID 37608896, 2023). "Further, analysis of IHC staining across all tumor sections showed a positive correlation between the intensity scores of CXCR7 and SYP, CXCR7, and CHGA." (PMID 37347559, 2023). "The upregulation of CHGA and UCHL1, which play a critical role in the oxidative stress response—an anti‐apoptotic function, is a unique feature of tumour cells." (PMID 37246623, 2023). "Immunohistochemical staining showed that tumor cells were positive for CD56, synaptophysin, and chromogranin A. Twenty-three days after the CT-guided PTNB, repeat CT scan showed that the tumor size regressed to 0.6 × 0.6 cm." (PMID 37878146, 2023).
tumor (continued). "Correlation of UCHL1 and CHGA expression with EMT‐related carcinogenesis signalling pathways, as a prognostic and predictive biomarker by immunohistochemical assay in CRC tumour tissues with lymph node metastasis (LNM) Stage III." (PMID 37246623, 2023). "The classic neuroendocrine markers (synaptophysin, chromogranin A, and NCAM) are usually used for diagnosis of the tumor biopsy sample and the cisplatin-etoposide combination is used as standard first line chemotherapy." (PMID 37608896, 2023). "Serum chromogranin A (CgA) and neuron-specific enolase (NSE) measurements have traditionally been considered as tumor markers for NENs." (PMID 37568540, 2023). "Immunohistochemical staining showed that the tumor cells were positive for CD56, synaptophysin, and chromogranin A." (PMID 37878146, 2023). "The same tumor cells were also positive for the neuroendocrine markers Synaptophysin (SYP) and Chromogranin (CHGA)." (PMID 35789568, 2022). "The profiled tumor cells expressed most general PNEC markers (e.g. SCG5, CHGB, SCG2, PCSK1N, CHGA, SCG3) indicating retention of PNEC identity." (PMID 36469459, 2022). "Immunohistochemical staining had revealed that the tumor cells were positive for CD56 and chromogranin A." (PMID 35351092, 2022). "Neuroendocrine cells express common classical markers, such as synaptophysin (more sensitive), chromogranin A (more specific) or CD56, whose determination is mandatory in order to confirm the neuroendocrine origin of the tumour." (PMID 35626118, 2022). "Tumor cells in MCC typically express markers of neuroendocrine and epithelial differentiation, such as neuron-specific enolase (NSE), CD56, chromogranin A, synaptophysin, and low molecular weight cytokeratins (CK8, CK18, CK19, CK20), CAM 5.2, and AE1/AE3." (PMID 36612102, 2022). "Although the expression of CHGA, NCAM1, and SYP varied among these three individuals, all of them showed a co-expression of AR and NE markers in the same areas of tumor sites." (PMID 36033483, 2022). "The neuroendocrine markers: Neuron Specific Enolase (NSE), chromogranin A, synaptophysin and CD56 were expressed in 100% of the tumor specimens in which they were tested." (PMID 35528006, 2022). "In the high-grade neoplasm group (total = 73), DLL3 H-score positively correlated with chromogranin A expression (p = 0.04)." (PMID 34568063, 2021). "Histological and immunoblot analysis revealed small round blue cell tumours poor in stroma that expressed NCAM1, synaptophysin (SYP), Chromogranin A (CGA) and MYCN in Rosa26_Alkal2;Th‐MYCN tumours, in agreement with NB." (PMID 33411331, 2021). "In immunohistochemical stains, the tumor cells were positive for CD56, synaptophysin, and chromogranin A. The Ki-67 proliferative index was ∼60%." (PMID 34567573, 2021). "In the future, we will analyze the relationship between the NB5 assay and prognosis and explore the relationship between tumor relapse and PHOX2B, TH, DDC, CHGA, and DCX expression." (PMID 34055604, 2021). "In our case, the tumor cells are strongly positive for cytokeratin (AE1/AE3) and INSM1, and scatteredly positive for chromogranin A, synaptophysin, and CD56." (PMID 34477164, 2021). "Immunohistochemical staining with synaptophysin, chromogranin A, and CD56 was confined to the tumor." (PMID 33388069, 2021). "The immunohistochemistry (IHC) analyses showed that tumor cells were positive for thyroid transcription factor-1 (TTF-1) and neuroendocrine markers, including chromogranin A, synaptophysin, INSM1 (insulinoma-associated protein 1), and CD56." (PMID 33352665, 2020). "In contrast, virtually all CDX tumor cells expressed neuron-specific enolase (NSE), chromogranin A, Ki67, and CD44 evidencing emergence of an AR-null, neuroendocrine-positive phenotype." (PMID 32313004, 2020). "Immunohistochemical staining of chromogranin A, synaptophysin, and CD56 suggested that the tumor was a GB-NET." (PMID 33108599, 2020).
tumor (continued). "The resected tumor was pathologically similar to the primary lung LCNEC and staining of the tumor was positive for chromogranin A and synaptophysin." (PMID 31678698, 2019). "The TMP panel included 7 proteins routinely used in diagnostic IHC including cytokeratins (KRT5 and KRT7), markers of stratified epithelia (P63), mesenchymal (Vimentin) and neuroendocrine (CHGA, SYP) differentiation, and primary tumour origin (TTF1)." (PMID 31537838, 2019). "The stained tumours in the untreated control group showed a high and specific expression of MTC markers chromogranin A, synaptophysin, and calcitonin, and were morphologically consistent with MTC." (PMID 31725814, 2019). "Median tumor marker levels were 3.2 x ULN (upper limit normal) for PSA, 6.1 x ULN (i.e. 518.0 ng/ml) for chromogranin A and 7.6 x ULN (i.e. 128.5 ng/ml) for NSE (neuron-specific enolase)." (PMID 30713600, 2019). "A detailed immunohistochemical analysis showed that the tumor was strongly positive for synaptophysin, CD56 and chromogranin A, with a Ki-67 labeling index greater than 80%." (PMID 30024526, 2018). "Although the primary tumor derived from PC3-652 was weakly positive compared to PC3-vector control by immunostaining for NED markers, chromogranin A (CGA) and synaptophysin (SYP), the kidney metastasis was negative for these markers." (PMID 29721191, 2018). "MTC is known to produce many tumor markers, including calcitonin, CEA, and chromogranin A. These markers can be easily detected with blood levels and immunohistological stains." (PMID 30223887, 2018). "Immunohistochemical staining showed that almost all tumor cells were positive for CD56, synaptophysin, and chromogranin A. Ki67 was detected in 15–20% of the tumor cells." (PMID 29052535, 2017). "Immunohistochemically, the neuroendocrine markers chromogranin A, synaptophysin, and NSE were limited to the NEC component of the primary tumor." (PMID 28248881, 2017). "Immunohistochemically tumor cells are positive for cytokeratin, estrogen receptors (ER), progesterone receptors (PR), neuron specific enolase (NSE), chromogranin A, and/or synaptophysin." (PMID 27840759, 2016). "A case with a histopathologic finding of small round cells with scant cytoplasm should be evaluated for synaptophysin, chromogranin A, and CD56 expression, followed by ultrastructural analysis to detect neurosecretory granules in the tumor cells." (PMID 27818885, 2016). "Since PACC can have heterogeneous tumor populations, which include neuroendocrine derived cancer cells, we stained for neuroendocrine markers, such as neuron specific enolase (NSE) and chromogranin A (CgA)." (PMID 27165126, 2016). "Immunohistochemical staining showed that the tumor was CD56 (+), chromogranin A (+), and synaptophysin (−)." (PMID 27840746, 2016). "Like our presenting case, the tumor cells stained positive to CEA, GCDFP-15, CK7, chromogranin A, progesterone and androgen receptors." (PMID 26055980, 2015). "Like chromogranin A, PHM and PAL are efficiently targeted to secretory granules in corticotrope tumor cells." (PMID 26475607, 2015). "Serum tumor markers including CEA, AFP, CA 12.5, CA 19.9, and NSE were within normal range while chromogranin A was moderately elevated." (PMID 24653852, 2014). "In patients with a primary NET, what is the diagnostic accuracy of the available biochemical markers (eg, chromogranin A and B, Serotonin, neuron-specific-enolase (NSE), tumor specific hormones) in detecting liver metastases?" (PMID 24366180, 2013). "Most of the tumor cells were found to have a positive reaction for pan-cytokeratin, CK7, TTF1, chromogranin A and synaptophysin." (PMID 23119202, 2012). "The neuroendocrine character has been observed in some tumor cells within some HCC nodules and elevated serum chromogranin A (CgA) also been reported in patients with HCC." (PMID 23173843, 2012). "Strong positive reactions for chromogranin A and NSE were observed in almost all tumor cells in the lesion." (PMID 20175936, 2010).
tumor (continued). "Immunohistochemically, chromogranin A showed diffuse and strong staining, and the MIB-1 labeling index was 18.3 ± 5.6, supporting the high proliferation of the tumor." (PMID 20398400, 2010). "The tumour usually spares the mucosa, infiltrates muscularis propria and peri-appendiceal fat and can stain positively for mucin, CEA, cytokeratin, lysozyme, chromogranin A, serotonin and synaptophysin." (PMID 19171048, 2009). "Immunohistochemically, the tumor cells were positive for major neuroendocrine markers, such as synaptophysin, NCAM (CD56), and chromogranin A (Fig. 2BCD)." (PMID 20062644, 2009). "In the present case, samples were positive for chromogranin A and synaptophysin, and had a Ki67 index of 20%–30%, but could not be categorized as having MiNEN because NEC accounted for only 20% of the total tumor." (PMID 40567873, 2026). "Tumor markers such as CA 19-9 are often elevated in the presence of PDAC, while specific NET markers such as chromogranin A may help diagnose the NET component." (PMID 40559084, 2025). "Univariate analysis did not identify a statistically significant relationship between DFS and variables including age, gender, smoking history, tumor localization, TTF-1, P40, chromogranin A, synaptophysin, adjuvant chemotherapy, adjuvant radiotherapy, or type of surgery." (PMID 41153253, 2025). "The addition of most established inflammation scores, but not dNLR, improved a prognostic model including age, chromogranin A, Ki‐67, performance status, tumour site and previous treatments in NET patients treated with PRRT." (PMID 38477040, 2025). "The addition of parameters based on albumin and CRP, but not dNLR, to a base model including age, chromogranin A, the cell proliferation marker Ki‐67, performance status, tumour site and previous treatments improved the predictive accuracy of the base model." (PMID 38477040, 2025). "The qPCR analysis provided further insights into these findings, revealing a downward trend in the mRNA expression of adrenomedullary markers (CHGA, SYP, PNMT, and TH) in PCC organoids compared to primary tumor tissue, and in adrenomedullary organoids compared to NAM tissue." (PMID 40576438, 2025). "Synaptophysin, chromogranin A, and CD56 are commonly used markers to identify NE differentiation and the non-NE markers include caudal-type homeobox 2 (CDX2), cytokeratin 7 (CK7), CK20, among others depending on the specific neoplasm." (PMID 41041158, 2025). "Tumor cells tested negative for SMARCA4 but were positive for Chromogranin-A(CgA), Synaptophysin (SYN), Insm-1, TTF-1 (partial), and Ki67 (90%)." (PMID 40661782, 2025). "The diagnosis of LCNEC is established through neuroendocrine morphological features and immunohistochemical detection of at least one neuroendocrine marker CD56, synaptophysin, or chromogranin A in no less than 10% of tumor cells." (PMID 41153253, 2025). "Subcutaneous transplant tumour tissues (H128-Mut, control), BPM tumour tissues, and LM tumour tissues were subjected to IHC analysis, which showed that H128-LM and H128-BPM still have the expression of neuroendocrine markers, including CD56, CHGA, SYP and INSM1 (P > 0.05)." (PMID 38644473, 2024). "In addition, proteins less abundant in the tumor, such as basigin, N-WASP, Galectin-3 (Gal-3), and chromogranin-A (CgA), were identified in this functional network." (PMID 39195201, 2024). "In addition, only rare CHGA positive cells were observed in the patient lymph node metastasis biopsy and the CU-PC01 PDX tumours." (PMID 38667288, 2024). "PanNETs are categorized as non-functional tumours secreting nonspecific peptides like chromogranin A, low quantity of hormones like pancreatic polypeptide and calcitonin and malignant in 50% to 90%, have an indolent behavior and a better prognosis." (PMID 39246612, 2024). "Tumor marker: Non-specific tumor markers include chromogranin A, pancreatic polypeptide, and neuron-specific enolase." (PMID 39211694, 2024).